CCL2 (C-C motif chemokine ligand 2)
Diseases named in the same sentence as CCL2 in open-access papers (continued):
Sharing a sentence is not in itself a finding about the gene and the disease.
tumor (continued). "The data showed that compared with untreated mice, the content of GM-CSF and CCL2 remarkably increased in lung tissues of 4T1 tumor-bearing mice post-radiotherapy." (PMID 37268941, 2023). "The chemokines, such as CXCL12, CCL20, CCL5, CCL28, and CCL2/22, guide the Treg homing to the tumor." (PMID 36479842, 2023). "We found that many myeloid cell markers were highly expressed in hybrid tumor cells, including Ly6e, Ly6c2, Ccl2, Nos2, Cxcl1, and Cxcl2." (PMID 37138326, 2023). "For example, tumor secretion of TNF-α induces the chemokines CCL2 and CCL8 by TAMs which recruits additional CCR2+ monocytes to the TME." (PMID 37114134, 2023). "Under pathological conditions, especially in GBM, GBM cells release multiple chemokines, such as MCP-1 and CCL2, which allow microglia to activate and accumulate in large numbers around the tumour." (PMID 37304305, 2023). "In OSCC, we demonstrated for the first time a possible link between MCs and tumor cells via CCL2 as a mediator, consistent with these results." (PMID 36835050, 2023). "Surprisingly, we did not observe a significant anti-proliferation effect when either the parental or CCL2 KO MSCs were co-cultured with tumor cells in vitro." (PMID 36672395, 2023). "The concentration of CCL2 in BC patients increased with advancing tumor stage, while the median level of CCR2 decreased with advancing stage." (PMID 37208442, 2023). "At 12 weeks of age, the average number of tumours in PyMT control mice was 6.95 ± 0.73 tumours, and in PyMT/CCL2 mice there were 8.24 ± 0.26 tumours." (PMID 37108548, 2023). "MDSCs navigate the tumor microenvironment through chemokine receptors 2 (CCR2); GBM tumors express two CCR2 ligands, CCL2 and CCL7, which cause the tumor to signal the infiltration of CCR2+ cells." (PMID 37275361, 2023). "The expression levels of monocyte chemokines (csf-1 and ccl-2) in tumor cells of mice treated with EGCG were lower, and the cytokine was skewed from M2-to M1, which was manifested as the decrease of IL-6 and TGF-β, and the increase of TNF-α." (PMID 37560476, 2023). "It is well documented that the presence of cytokines such as IL-1, IL-6, and TNF-α or chemokines such as CCL2 and CXL8 from white blood cells or tumor-associated macrophage (TAMs) generate cancer-related inflammation in tumors." (PMID 36900505, 2023). "CCL2 plays a role in the recruitment of immune cells to the tumor microenvironment, but in cancer, it is known to influence malignancy and metastasis." (PMID 37239133, 2023). "Various cells, including tumor cells, endothelial cells, and fibroblasts, secrete CCL2, which promotes the recruitment of monocytes from the periphery towards the tumor site, leading to their differentiation into TAMs and subsequent tumorigenic development." (PMID 37313405, 2023). "CCL2 is one of the main regulators of monocyte and macrophage recruitment to the sites of inflammation that also promotes tumor dissemination, invasion, and immune evasion." (PMID 38138107, 2023). "In the context of tumors, CCL2 produced by tumor cells and/or tumor stromal cells is released into the circulation and engages with CCR2 expressed on monocytes." (PMID 37108657, 2023). "The role of CCL2-suppressed MSCs in cancer growth was examined by proliferation assays in vitro and a syngeneic mouse tumor model." (PMID 36672395, 2023). "CCL2, ARG1, ARG2, NOS2, and CCL5 are well-known N2-associated cytokines that promote tumor growth, invasion, and immune suppression." (PMID 37174093, 2023). "CCL2 influences tumor vascularization and metastasis by targeting vascular endothelial cells through the Janus kinase 2 (JAK2)-STAT5 and p38 mitogen-activated protein kinase pathways." (PMID 37373025, 2023). "Although primary tumors developed in all three mouse strains, the growth of the primary tumor was significantly delayed in Ccl2-/- and Ccr2-/- mice compared with WT mice." (PMID 37208442, 2023).
tumor (continued). "In OC patient, CCL2 is overexpressed in primary tumor cells and its receptor, CCR2, has been observed in TAMs isolated from OC patients." (PMID 37932814, 2023). "CCL2 was reported to mediate the recruitment of neutrophils, which are thought to facilitate tumor progression through CCL2 expression." (PMID 38057698, 2023). "PDIA3 expression in tumor cells promotes microglia polarization toward the M2 phenotype and releases mediators such as CCL2 and COX-2 to activate the JAK/STAT pathway." (PMID 37700840, 2023). "CCL2 is a chemokine produced by cancer cells that attracts tumor-promoting macrophages to the tumor site." (PMID 37345170, 2023). "Mechanistically, LNMAT1 recruited hnRNPL-mediated H3 lysine 4 trimethylation (H3K4me3) to the CCL2 promoter and epigenetically activated CCL2 expression to recruit TAMs in the tumor microenvironment." (PMID 37637063, 2023). "Anti-CCL2 antibodies have been shown to inhibit tumor growth in several animal models, such as glioma, colon cancer, prostate cancer, and melanoma." (PMID 36739406, 2023). "Cells expressing the CCL2-receptor CCR2 on their cell surface can migrate along a CCL2 gradient to the peripheral tumor site." (PMID 37849753, 2023). "STAT3 can also activate CCL2 (MCP-1), promoting inflammation that supports tumor growth in the liver." (PMID 37958504, 2023). "TAp73 (one kind of tumor suppressor) inhibits NF-κB-mediated CCL2 secretion and TAM recruitment, which reduces BC growth and metastasis." (PMID 36765683, 2023). "In the state of CCL2 disorder, macrophage recruitment into the microenvironment of tumour and result in distant metastasis and reduced survival rate." (PMID 36872292, 2023). "CCL2 was initially discovered as a tumor-derived chemoattractant which recruits monocytes/macrophages to tumor tissue." (PMID 36260158, 2023). "In this study, MYBL2 transcriptionally activated CCL2 and further promoted the recruitment and M2-like polarization of macrophages, thereby inducing tumor progression and anti-PD-1 therapy tolerance." (PMID 37865750, 2023). "A second CCL2 inhibitor mNOX-36 has been shown in a rat model of GBM to significantly inhibit tumor growth." (PMID 37114134, 2023). "By promoting epithelial-mesenchymal transition (EMT) and cancer cell extravasation, CCL2 encourages tumor metastasis." (PMID 37941832, 2023). "CCL2 blockade can stop tumor spread, angiogenesis, and growth, and researchers have demonstrated CCL2 restriction in animal studies to increase the antitumor effects of cytotoxic T lymphocytes and decrease the number of TAMs in the TME." (PMID 38033495, 2023). "Evidence suggests that tumor derived chemokines and cytokines including CCL2, CSF1, ECM components and hypoxia are involved in the recruitment of monocytes/macrophages." (PMID 37656220, 2023). "In the 4T1 tumor model, IL-1β was found to promote the differentiation of tumor-infiltrating inflammatory monocytes into macrophages by inducing the production of chemokine (CC-motif) ligand 2 (CCL2)." (PMID 38066523, 2023). "Cytokines as IL-8, IL-33, IL-10, TGF-β and CCL2 secreted by CAFs promoted the recruitment of monocytes at tumor site and the M2-like protumor phenotype." (PMID 37342322, 2023). "CXCL1 induces the recruitment of neutrophils into the HCC tumor niche; these cells secrete CCL2 and C-C motif ligand 17 (CCL17, thymus and activation-regulated chemokine (TARC)), which induce the recruitment of monocytes and Treg, respectively." (PMID 37408240, 2023). "In contrast, we observed a significant reduction in M1 gene markers in the spleens of tumor-bearing mice, whereas inconsistent changes were observed for the M2 markers (higher levels of Arg1 and lower levels of CCL2 and CD163)." (PMID 37628775, 2023). "In a model of Hepa 1-6 cell-derived liver tumors, developed in otherwise unchallenged mouse livers, CCL2/CCR2 blockade attenuated tumor growth, altered TAM phenotype and restored CD8+ T cell activity." (PMID 36845555, 2023).
tumor (continued). "According to recent data, tumor-infiltrating macrophages have been mostly described in those PitNETs with hypersecretion of CCL2, CCL3, CCL4, and IL-8." (PMID 37958702, 2023). "Bindarit is a small molecule drug that inhibits the synthesis of CCL2 and has been shown to induce tumor regression in preclinical studies by inhibiting TAM and MDSC infiltration of the TME in breast cancer, prostate cancer, and osteosarcoma animal models." (PMID 37114134, 2023). "This analysis revealed that while in the heart of PyMT-bearing mice, INFγ and TNFα are at low levels; IL-13 and CCL2 are elevated in the PyMT tumor." (PMID 37508517, 2023). "CCL2 inhibition in an in situ BC mouse model suppressed tumor growth, decreased MDSCs and Tregs, and fostered tumor immune suppression." (PMID 37743226, 2023). "In tumor-bearing WT mice, the serum CCL2 concentration markedly increased 1 week after inoculation of 4T1 cells, peaked at 2 weeks, and decreased thereafter despite the primary tumor continuing to grow." (PMID 37208442, 2023). "The aggressiveness of this tumour development limited our analysis of the effect of CCL2 on early tumorigenesis and hyperplasia." (PMID 37108548, 2023). "Studies have reported that CCL2 recruits cytotoxic γδ T lymphocytes in vitro, and to tumour sites in vivo." (PMID 37108548, 2023). "The authors identify a tumor-suppressing angiocrine function of CCL2 which is inhibited by tumor-derived adrenomedullin acting via its receptor on endothelial cells." (PMID 36374225, 2023). "Taken together, these results show that IL‐1β secreted by Mφ stimulates CCL2 secretion in tumor cells, which in turn boosts Mφ infiltration, thus further increasing PD‐L1 expression in tumor cells and orchestrating tumor immunosuppressive microenvironment." (PMID 37009412, 2023). "At 9 weeks of age, 100% of the primary tumours from both PyMT and PyMT/CCL2 mice were in the late carcinoma stage." (PMID 37108548, 2023). "Chemokine (C–C pattern) ligand 2 (CCL2) regulates progression to cells in the tumor microenvironment as well as cancer." (PMID 37639070, 2023). "At 9 weeks of age, the average primary tumour weight was 124.28 ± 15.48 mg for PyMT controls and 145.33 ± 41.62 mg in PyMT/CCL2 mice." (PMID 37108548, 2023). "Among them, CCL2 facilitates the mobilization of receptor CCR2+ inflammatory monocytes from bone marrow to the tumor bed, where they become immunosuppressive TAMs." (PMID 37444617, 2023). "Tumor tropism of adoptively transplanted T lymphocytes by controlling tumor chemokine release to glioblastoma expressing CCL2, (a ligand for CCR4) has been demonstrated." (PMID 36721153, 2023). "Another work in the B16.F10 model also demonstrated that TLR7/9 stimulation with imiquimod can trigger CCL2 release by MCs to efficiently recruit plasmacytoid DCs at the tumor site, which, in turn, can directly kill tumor cells via TRAIL and granzyme B." (PMID 37376140, 2023). "TAMs with Notch activation induce the secretion of CCL2, further amplifying M-MDSCs recruitment and attenuating anti-tumor immune response of T cells." (PMID 37131214, 2023). "The activation of the CCL2/CCR2 axis, which mediates the crosstalk between tumor-associated macrophages (TAMs) and tumor cells, is associated with angiogenesis, metastases, immunosuppression, and cancer progression." (PMID 37626858, 2023). "In tumor immunotherapy, blocking the CCL2 signaling pathway can effectively reduce the infiltration of M2 macrophages and enhance the antitumor immune response to achieve the purpose of tumor treatment." (PMID 37926835, 2023). "Others have shown that the chemokine CCL2 induces tumor proliferation and migration by activating the Akt pathway and matrix metalloproteases." (PMID 37373544, 2023). "This was confirmed by the observation of a significant positive correlation between IL‐1β and CCL2 levels in ID8 tumor tissues and LLC tumor tissues." (PMID 37009412, 2023).
tumor (continued). "This enhanced 15-LOX2/15(S)-HETE activity in the RCC tumor microenvironment positively affects the production of the proinflammatory chemokine CCL2 and immunosuppressive cytokine IL-10, thus promoting local immunosuppression and tumor evasion." (PMID 36834678, 2023). "Recently, CREBBP LOF has also been proposed to increase the expression of CSF1 and CCL2 in DLBCL tumor cells, thereby promoting tumor-associated macrophage recruitment and polarization towards immunosuppressive macrophages." (PMID 38022603, 2023). "Generally, CCL2 promotes tumor-growth through process, like inducing angiogenesis, recruiting MDSCs and metastasis-promoting monocytes, while it also has anti-tumor capability by driving tumor cell apoptosis." (PMID 36747118, 2023). "For instance, in cholangiocarcinoma, CCL2 produced by CAFs 69, leads to tumor progression, modulating metastasis, angiogenesis and cancer proliferation." (PMID 37324191, 2023). "In cancer, several studies highlighted the importance of CCL2 in promoting monocyte migration from the bone marrow to the circulation and ultimately to the tumor site, where they elicit immune suppressive activity and stimulate tumor growth." (PMID 37251376, 2023). "Disinhibition of endothelial CCL2 results in reduced tumor progression through inhibition of adrenomedullin formation by tumor cells." (PMID 36374225, 2023). "Silencing CCL2 was found to inhibit the development of TNBC by blocking tumor stem cell self-renewal and M2-type macrophage recruitment." (PMID 36959811, 2023). "For instance, the cessation of anti-CCL2 treatment has been observed to enhance tumor angiogenesis and metastasis due to rebounding monocyte recruitment." (PMID 37626849, 2023). "The CCR2/CCL2 axis is a known contributor to tumour cell survival and invasion, angiogenesis, and the recruitment of immune cells." (PMID 37170733, 2023). "β2AR signaling can also polarize macrophages from M1 to M2 type, thereby enhancing anti-inflammatory cytokines like IL-10, IL-4 & IL-13, and decreasing pro-inflammatory cytokines like INFγ, TNFα, IL1β, CCL2, CCL3 and CCL4 to cause tumor progression." (PMID 37006295, 2023). "The two Fn-Dps-treated groups had more tumor nodules distributed on the liver surface (P<0.01), while fewer metastases were observed in the CCL2/7 nAb + Fn-Dps group (P<0.05)." (PMID 36693067, 2023). "CCL2 is secreted by different cell types, like T cells, monocytes, and also tumor cells, and works as a chemoattractant for myeloid cells, activated CD4+ and CD8+ T cells, and NK cells." (PMID 37284199, 2023). "Further, monocyte chemoattractant protein-1 (CCL2) was highly upregulated in the irradiated tumor, forming a potential basis for its high level of monocyte infiltration." (PMID 37209684, 2023). "Treg recruitment was associated with the chemokines CCL2, CCL17 and CCL22 secreted by tumor cells and TAMs, which significantly induced Treg migration." (PMID 37598158, 2023). "The ability of dysadherin to promote tumor cell invasion in vitro was dependent on a CCL2 autocrine loop, and CCL2 secreted by dysadherin-positive tumor cells also promoted EC migration in a paracrine fashion." (PMID 37208442, 2023). "CCL2 and E-selectin themselves can also directly facilitate the extravasation and metastasis of tumor cells." (PMID 37046617, 2023). "B cells can capture tumor antigens and activate immune cells in the initial stage of the immune response, or participate in tumor killing by secreting antibodies, such as CCL2, CXCR4, CCL5, CXCL5 and CXCL10, which trigger the activation of CD4 and CD8 T cells." (PMID 37254219, 2023). "Tumor‐associated macrophages (TAMs) and regulatory T cells (Treg) are recruited by chemokine C–C motif ligand 2 (CCL2) from primary tumor cells to form PMNs in the lung." (PMID 37902101, 2023).
tumor (continued). "In the setting of murine GBM, research has shown that neoplastic cells in GBM express high levels of CCL2, which contributes to the directional infiltration of CCR2Hi inflammatory monocytes into the tumor." (PMID 37190507, 2023). "Both immune cell-driven CCL2/7 can enhance tumor metastasis by promoting EMT or recruiting macrophages in CRC." (PMID 36693067, 2023). "CCL2 immunoreactivity was present in tumor cells in 17 of 97 (18%) tumors but also in TAMs, fibroblasts, and ECs in the majority of tumors." (PMID 37208442, 2023). "Levels of inflammatory cytokines and chemokines, including IL-6 and CCL2, in tumor cells increased in serum globular tumor tissues, which showed an increase in tumor cells." (PMID 37639070, 2023). "The correlation between the tumor CCL2 mRNA expression level and survival was analyzed in some of the studies introduced in this review." (PMID 37208442, 2023). "At 12 weeks of age, the average primary tumour weight was 588.39 ± 64.30 mg in PyMT control mice and 613.29 ± 104.01 mg in PyMT/CCL2 mice." (PMID 37108548, 2023). "Nevertheless, in a mouse model, CCL2 overexpression induced a sustained autoantibody production and significantly limited tumor growth, suggesting a potential beneficial role of these autoantibodies." (PMID 37251376, 2023). "The CCL2 concentration in tumor homogenates was positively correlated with the level of cytokines with angiogenic activity, such as vascular endothelial growth factor (VEGF), tumor necrosis factor (TNF) α, CXCL8 and thymidine phosphorylase (TP)." (PMID 37208442, 2023). "IL-4, TGFβ and IL-8 were assessed in low amounts (471 to 820 pg/mg of tumor); CCL2, IL-12, IL-6 and IL-10 in moderate amounts (2825 to 3440 pg/mg of tumor); and IFNγ, TNFα, IL-1β and IL-2 in high amounts (6293 to 13,492 pg/mg of tumor)." (PMID 37526660, 2023). "Many proteins impact CCL2 expression in tumor cells (e.g., inflammatory mediators such as interleukin-1, interleukin-6, tumor necrosis factor-alpha (TNFα) or transforming growth factor-β (TGFβ))." (PMID 37176074, 2023). "Based on the results, the level of ANPEP, HLA‐A, CCL2, TLR4 and SERPINE1 had statistically significant association with tumor purity in UCEC tissues." (PMID 36969077, 2023). "Both the CCL5 and CCL2 chemokines recruit MDSCs to the tumor site, and the CAF-MDSC axis affects ROS levels." (PMID 37430270, 2023). "Chemokines such as CCL2 and G-CSF, which are secreted by tumor or endothelial cells, are responsible for leukocyte attraction." (PMID 37994159, 2023). "Since its discovery in 1989, many studies have been conducted to define the biological role of tumor-derived CCL2 and the mechanisms regulating CCL2 production during the development and progression of BC both in vitro and in vivo." (PMID 37208442, 2023). "This signature of reduced CCL2 signaling, myeloid cell infiltration, and TAM2-polarization has previously been associated with a predominantly anti-tumor microenvironment, resulting in an attenuated HCC burden." (PMID 37620309, 2023). "CCL2 is produced by various cells, including mesenchymal stem cells, leukocytes, fibroblasts, and tumor cells in the TME, acting as a chemoattractant for diverse types of immune cells." (PMID 36674955, 2023). "Active monocyte recruitment required tumor-derived chemokine releases, such as CCL2, CCL3, CCL4, CCL5, CCL20, and CCL18." (PMID 36765694, 2023). "The production of G-CSF and CCL2 by a primary tumor in a mouse model of breast cancer induced the recruitment and activation of neutrophils in the pre-metastatic lung along with the killing of cancer cells mediated by ROS." (PMID 37444436, 2023). "The average number of tumours in PyMT control mice was 3.36 ± 0.26 tumours and in PyMT/CCL2 mice, there were 2.8 ± 0.21 tumours at 9 weeks of age." (PMID 37108548, 2023). "Spleens of tumor bearing mice over express CCR2 ligand CCL2, along with the CXCR2 ligands CXCL2 and CXCL5." (PMID 37380989, 2023).